COL1A2 (collagen type I alpha 2 chain)
Diseases named in the same sentence as COL1A2 in open-access papers (continued):
Sharing a sentence is not in itself a finding about the gene and the disease.
osteogenesis imperfecta (continued). "The large majority of osteogenesis imperfecta (OI) arises from pathogenic variants in COL1A1 or COL1A2 which encode type 1 collagen." (PMID 37675393, 2023). "Mutations in the type I collagen coding genes (COL1A1 and COL1A2) affecting collagen quantity or structure count for approximately 85% of osteogenesis imperfecta (OI) cases." (PMID 36923788, 2023). "Osteogenesis imperfecta (OI) is a heritable connective tissue disorder caused by mutations in COL1A1 or COL1A2, leading to defective collagen synthesis and ECM organization, and is primarily studied in skeletal tissue." (PMID 37623368, 2023). "Osteogenesis imperfecta (OI) is a genetic disorder of connective tissue generally associated with pathogenic variants in COL1A1 or COL1A2 genes." (PMID 37375779, 2023). "COL1A2 deficiencies cause Osteogenesis Imperfecta (OI) which manifests overlapping features with SWS as blue sclerae, bone fragility and hearing loss." (PMID 36393834, 2022). "Osteogenesis imperfecta (OI) is a genetic disorder that affects bone strength as a result of mutation in the genes (COL1A1/COL1A2) responsible for collagen type I production." (PMID 36354587, 2022). "Mutations in the type I collagen coding genes (COL1A1 and COL1A2) that affect collagen quantity or structure count to approximately 85% of osteogenesis imperfecta (OI) case." (PMID 34567078, 2021). "Osteogenesis imperfecta (OI) is a heritable form of bone fragility typically associated with a dominant COL1A1 or COL1A2 mutation." (PMID 19594296, 2010). "Osteogenesis imperfecta (OI) is a genetic disorder of bone fragility caused by defects in either the pro-α1(I) (COL1A1) or pro-α2(I) (COL1A2) genes encoding type I collagen." (PMID 23675157, 2009). "Osteogenesis imperfecta (OI) most commonly results from heterozygous dominant COL1A1 or COL1A2 variants (~85% of classic cases), with additional dominant or recessive defects in collagen-processing genes producing a spectrum from mild (Type I) to perinatal lethal (Type II) disease." (PMID 41511357, 2026). "Osteogenesis Imperfecta (OI) is a heritable connective tissue disorder primarily caused by pathogenic variants in COL1A1 and COL1A2, encoding the pro-α chains of type I collagen." (PMID 41602857, 2026). "Pharmacologically,GalNAc-Apc001 exhibited superior therapeutic efficacy by mitigatingthe suppressive effects of sclerostin on Wnt signaling, upregulatingbone formation markers, and enhancing bone mass in a Col1a2+/G610C osteogenesis imperfecta mousemodel." (PMID 41450662, 2025). "Whole-exome sequencing studies, for instance, have linked mutations in COL1A2 and EN1 to osteogenesis imperfecta, a monogenic disorder characterized by extreme bone fragility." (PMID 40411668, 2025). "Osteogenesis imperfecta is usually associated with mutations in the genes encoding collagen type 1, COL1A1, and COL1A2." (PMID 40136761, 2025). "Osteogenesis imperfecta (OI) is a genetic disorder resulting from gene mutationsencoding type 1 collagen, COL1A1, and/or COL1A2." (PMID 40630436, 2025). "Osteogenesis imperfecta or an increased fracture risk can also be caused by mutations in collagen genes COL1A1 and COL1A2." (PMID 41141281, 2025). "Osteogenesis Imperfecta (OI) is a rare genetic disorder characterized by defects in type I collagen synthesis due to mutations in the COL1A1 and COL1A2 genes, inherited in an autosomal dominant manner." (PMID 39797138, 2024). "Osteogenesis imperfecta (OI) is a rare genetic disorder of connective tissue, caused by inherited mutations of the genes COL1A1 or COL1A2 in approximately 90% of cases." (PMID 39767599, 2024). "Osteogenesis imperfecta (OI) arises from a collagen type 1 defect due to several gene mutations, particularly COL1A1 and COL1A2." (PMID 39156321, 2024).
osteogenesis imperfecta (continued). "Access to musculoskeletal services can address their needs, and the condition is often well managed through services that also have experience with osteogenesis imperfecta (OI) which is the most common manifestation of heterozygous pathogenic variants in COL1A1 or COL1A2." (PMID 39629459, 2024). "Osteogenesis imperfecta (OI) is a rare genetic disorder commonly caused by variants of the type I collagen genes COL1A1 and COL1A2." (PMID 39012717, 2024). "Osteogenesis imperfecta (OI) is an inherited disorder characterized by bone fragility with extraskeletal manifestations mostly due to COL1A1 and COL1A2 variants." (PMID 39450342, 2024). "Osteogenesis imperfecta (OI) describes a group of inherited disorders, most often due to mutations in type I collagen genes (COL1A1, COL1A2) by an autosomal dominant inheritance." (PMID 39274387, 2024). "The osteogenesis imperfecta mutant mouse (OIM), which has a recessive mutation in the Col1a2 gene, models the human connective tissue disorder osteogenesis imperfecta." (PMID 37681905, 2023). "Pathogenic variants in FGFR3, COL1A1, COL1A2, and COL2A1 are common causes of isolated short stature or osteogenesis imperfecta." (PMID 36923788, 2023). "Osteogenesis imperfecta type I in the majority of cases (~95%) is caused by mutations in the COL1A1 and COL1A2 genes; hence, in this study, we focused on sequencing analyses of those genes." (PMID 37895885, 2023). "The aim of this study was to identify and analyze the expression profiles of miRNAs in osteogenesis imperfecta (OI) type I caused by mutations in the COL1A1 and COL1A2 genes." (PMID 37895885, 2023). "Osteogenesis imperfecta (OI) is a group of autosomal dominant genetic diseases associated with pathogenic variants of the COL1A1 and COL1A2 genes." (PMID 36831000, 2023). "Osteogenesis imperfecta was formerly thought to be a dominantly inherited disease produced by mutations in either of the type I collagen genes (COL1A1 and COL1A2)." (PMID 35399624, 2022). "Some studies have reported that COL1A2 is involved in regulation of the osteoarthritis, Ehlers-Danlos syndrome, osteogenesis imperfecta." (PMID 35359458, 2022). "Osteogenesis imperfecta is mostly caused by mutations in the COL1A1 (17q21.33) and COL1A2 (7q21.3) genes." (PMID 33920808, 2021). "Osteogenesis imperfecta (OI), a genetic disease caused by defective synthesis of type I collagen, is associated with mutations in the COL1A1 and COL1A2 genes." (PMID 34300306, 2021). "Osteogenesis Imperfecta (OI) is a genetic disorder also known as ‘brittle bone disease’ Autosomal dominant mutations in the type I collagen coding genes (COL1A1 and COL1A2) affect the collagen structure in the majority of OI patients." (PMID 33743784, 2021). "It has been demonstrated that osteogenesis imperfecta in humans, which is characterized by a tendency for bone fractures, is caused by mutations in either the COL1A1 or COL1A2 genes encoding type I collagen." (PMID 33029260, 2020). "Osteogenesis imperfecta (OI) is an autosomal dominant form of osteoporosis most often caused by mutations in type I collagen genes (COL1A1, COL1A2)." (PMID 33066607, 2020). "For example, in the osteogenesis imperfecta murine (oim) model, a single nucleotide deletion in the Col1a2 gene, resulted in a normal size mRNA, but fail to secrete the protein." (PMID 33370286, 2020). "Supporting our postulation, osteogenesis imperfecta, caused by heterozygous mutations in type 1 procollagen genes (COL1A1/COL1A2), is associated with communicating hydrocephalus." (PMID 32353054, 2020). "The most common form is osteogenesis imperfecta linked to mutations in COL1A1 and COL1A2, the two genes encoding type I collagen." (PMID 30858824, 2019). "Osteogenesis imperfecta (OI) is a rare genetic disorder of the connective tissue and 90% of cases are due to dominant mutations in COL1A1 and COL1A2 genes." (PMID 30886339, 2019).
osteogenesis imperfecta (continued). "Osteogenesis imperfecta (OI), or “brittle bone disease,” is caused by mutations in the collagen type I genes COL1A1 and COL1A2 (or other collagen genes for rarer types of OI), causing production of a defective collagen type I that results in significant alterations in different tissues in the body." (PMID 30128210, 2018). "Mutations in the COL1A1 and COL1A2 genes are known to cause rare forms of Ehler’s Danlos Syndromes, types VIIA and B and osteogenesis imperfecta types I and II." (PMID 28346524, 2017). "The more prevalent autosomal dominant forms of osteogenesis imperfecta are caused by mutations in the COL1A1 and COL1A2 genes, which encode the α1- and α2-chains of type I procollagen, respectively." (PMID 28208663, 2017). "Osteogenesis imperfecta (OI) is a heterogeneous group of disorders of connective tissue, caused mainly by mutations in the collagen I genes (COL1A1 and COL1A2)." (PMID 28498836, 2017). "The majority of Osteogenesis Imperfecta (OI) cases are caused by mutations in one of the two genes, COL1A1 and COL1A2 encoding for the two chains that trimerize to form the procollagen 1 molecule." (PMID 24767406, 2014). "Osteogenesis imperfecta (OI) is a genetic disorder of MSC due to mutations in the COL1A1 and COL1A2 genes characterized by production of defective type I collagen, generalized osteopenia that leads to bone deformities and fractures in children." (PMID 23766767, 2013). "Osteogenesis Imperfecta (OI) is a heritable connective tissue disorder mainly caused by mutations in the genes COL1A1 and COL1A2 and is associated with hearing loss in approximately half of the cases." (PMID 22206639, 2011). "The efficiency of the new process is shown by confirmation of the identification of the Col1A2 locus in osteogenesis imperfecta patients from Amish families." (PMID 19331686, 2009). "DGI type I is inherited with osteogenesis imperfecta and recent genetic studies have shown that mutations in the genes encoding collagen type 1, COL1A1 and COL1A2, underlie this condition." (PMID 19021896, 2008). "Osteogenesis imperfecta is an autosomal dominant condition usually resulting from mis-sense mutations affecting either of the two genes encoding type I collagen (COL1A1 and COL1A2)." (PMID 19021896, 2008). "Following this example, I propose to define osteogenesis imperfecta as syndromes resulting from mutations in either COL1A1 or COL1A2 genes, and to group all other syndromes with congenital brittle bones as "syndromes resembling OI" (SROI), pending the identification of their causal mutation." (PMID 15339338, 2004). "Osteogenesis imperfecta (OMIM #166200) is a genetic disorder primarily affecting connective tissues due to mutations in the Collagen Type I Alpha 1 Chain (COL1A1) and Collagen Type I Alpha 2 Chain (COL1A2) genes, which code for the α1 and α2 chains of type 1 collagen." (PMID 40004475, 2025). "Similar findings have been reported for mutations in COL1A1 and COL1A2 that cause osteogenesis imperfecta, and whilst some mutations trigger the UPR, others do not." (PMID 41465495, 2025). "Osteogenesis Imperfecta (OI), commonly defined as ‘brittle bones’ disease, is pathogenetically based on an hereditary collagen type I synthesis disorder, most often due to an autosomal dominant mutation in COL1A1 or COL1A2 genes." (PMID 38347577, 2024). "Patient with LP variant c.670C > T; p.(Arg224Cys) in COL1A2 present no involvement of other vascular districts and no signs of CTDs and/or osteogenesis imperfecta." (PMID 39654947, 2024). "Specific pathogenic variants in the type I collagen genes COL1A2 or COL1A1 may present with (classical) EDS features, sometimes overlapping with osteogenesis imperfecta-related bone fragility." (PMID 39629471, 2024). "Interestingly, similar craniofacial abnormalities are seen in osteogenesis imperfecta, which is also caused by variants in COL1A1 or COL1A2 and can show clinical overlap." (PMID 36756177, 2023).
osteogenesis imperfecta (continued). "Osteogenesis imperfecta (OI) is a rare inheritable skeletal disorder, caused, in most cases, by structural or quantitative defects in the α1 and α2 chains of collagen type I, encoded by COL1A1 or COL1A2 genes, respectively." (PMID 37643181, 2023). "The most notable syndrome with dentin malformations as a phenotype is osteogenesis imperfecta (OI), which affects one in 15,000–20,000 births, with over 85% of cases being autosomal dominant OI types I-IV, caused by defects in COL1A1 and COL1A2, encoding type I collagen." (PMID 35627243, 2022). "On the other hand, for a patient who is highly suspected to have Osteogenesis Imperfecta (OI), a disease where large number of sequence variants in the COL1A1 and COL1A2 gene can be causative, a sequencing panel targeting those two genes would be most appropriate." (PMID 34071827, 2021). "Supporting our hypothesis, osteogenesis imperfecta, that is caused by mutations in type 1 procollagen genes (COL1A1/COL1A2), is associated with communicating hydrocephalus." (PMID 32069308, 2020). "Aside from the pathogenic variants in COL1A1, COL1A2 and CREB3L1, we were unable to identify any other mutual variant related to collagen type I that could explain the phenotype with osteogenesis imperfecta and oligodontia." (PMID 32234057, 2020). "Haploinsufficiency or gain of function mutations in COL1A1 and COL1A2, coding for the pro-collagen I chains, can cause different forms of osteogenesis imperfecta (OI) with (OMIM #259420) or without dentinogenesis imperfecta (DGI)." (PMID 32101163, 2020). "Novel pathogenic variants were represented by 27 (42.85%) variants (20 in COL1A1; 7 in COL1A2) absent from the osteogenesis imperfecta variant database." (PMID 31447884, 2019). "Approximately 90% of osteogenesis imperfecta cases are due to causative variants in the COL1A1 and COL1A2 genes, which result in abnormal collagen I fibrils formation, while the remaining 10% of cases are associated with recessive variants of known or yet to be discovered genes." (PMID 31299979, 2019). "In four patients harboring COL1A2 mutations, the phenotype of osteoporosis was indistinguishable from mild osteogenesis imperfecta in young and middle‐aged adults." (PMID 30283887, 2018). "Osteogenesis Imperfecta (OI): OI, also known as brittle bone disease, is characterized by brittle bones that are prone to fracture and are caused by mutations in the COL1A1 or COL1A2 genes in the majority of cases." (PMID 25621177, 2014). "Osteogenesis imperfecta (OI) is a remarkably heterogeneous monogenic disease characterized by bone fragility and low bone mass, more than 90% of which are caused by dominant mutations in encoding genes of type I procollagen chains proα1 (COL1A1, MIM 120150) or proα2 (COL1A2, MIM 120160)." (PMID 25238597, 2014). "Osteogenesis imperfecta (OI) is a disorder with heterogeneous genetic causes that prominently include mutations in the type I collagen genes, COL1A1 and COL1A2." (PMID 37546916, 2023). "Osteogenesis imperfecta (OI) is a rare (~11 per 100,000), inherited systemic connective tissue disease largely caused by mutations in the COL1A1 or COL1A2 genes." (PMID 37623368, 2023). "Osteogenesis imperfecta (OI) is a rare disorder of abnormal production or modification of type I collagen, which is caused by mutations in COL1A1, COL1A2 or other genes." (PMID 36339400, 2022). "Osteogenesis imperfecta (OI) is the most common monogenic disease of the skeletal system and is usually caused by mutations in the COL1A1 or COL1A2 genes." (PMID 35804365, 2022). "The inherited brittle bone disease osteogenesis imperfecta (OI) is commonly caused by COL1A1 and COL1A2 mutations that disrupt the collagen I triple helix." (PMID 35701367, 2022).
osteogenesis imperfecta (continued). "Osteogenesis imperfecta (OI) is a rare inherited connective tissue dysplasia characterized with skeletal fragility, recurrent fractures and bone deformity, predominantly caused by mutations in the genes COL1A1 or COL1A2 that encode the chains of type I collagen." (PMID 35154279, 2022). "Osteogenesis imperfecta (OI) is a group of rare genetic disorders caused mostly by pathogenic variants in the COL1A1 and COL1A2 genes, inherited in an autosomal dominant manner." (PMID 35893298, 2022). "Nearly 85%-90% of osteogenesis imperfecta (OI) cases are caused by autosome dominant mutations of COL1A1 and COL1A2 genes, of which de novo mutations cover a large proportion, whereas their characteristics remain to be elucidated." (PMID 35909573, 2022). "Osteogenesis Imperfecta (OI) is a rare inheritable condition commonly caused by mutations in genes (COL1A1 and COL1A2) encoding collagen type I which is essential for healthy bone formation." (PMID 34569391, 2021). "Osteogenesis imperfecta (OI) represents a complex spectrum of genetic bone diseases that occur primarily due to mutations and deletions of the COL1A1 and COL1A2 genes." (PMID 34946798, 2021). "Osteogenesis imperfecta (OI), a congenital bone disorder, is caused by mutations in COL1A1 and COL1A2 genes, leading to deficiency of type I collagen." (PMID 26307460, 2015). "Osteogenesis imperfecta (OI) is a genetic disorder of connective tissue characterized by increased bone fragility and low bone mass due to mutations in the genes encoding type I collagen, particularly COL1A1 and COL1A2." (PMID 40171373, 2025). "In addition, 20 patients were diagnosed with Osteogenesis Imperfecta (OI) (OMIM: #166210, #259420, #166220), with ten patients showing variants in the COL1A2 gene (OMIM: *120160) and eight patients with variants in the COL1A1 gene (OMIM: *120150)." (PMID 40130161, 2025). "Osteogenesis Imperfecta (OI) is a connective tissue disorder caused by defects in genes encoding type I collagen (COL1A1 and COL1A2) or proteins responsible for synthesis, posttranslational modification and transport of collagen type I. This results in aberrant bone formation." (PMID 35546999, 2022). "Osteogenesis imperfecta/Ehlers−Danlos (OI/EDS) overlap syndrome is a recently described disorder of connective tissue, characterized by mutation of COL1A1 (17q21.33) or COL1A2 (7q21.3) genes, that are involved in α-1 and α-2 chains of type 1 collagen synthesis." (PMID 35456387, 2022). "Osteogenesis imperfecta (OI) is a clinically and genetically heterogeneous group of heritable disorders of connective tissue which is caused by dominant mutations in collagen type I, encoded by COL1A1 and COL1A2 in up to 90% of cases." (PMID 33743023, 2021). "Osteogenesis imperfecta (OI) is a genetic disorder characterized by defects in COL1A1 and COL1A2, affecting bone, skin, and other tissue with high collagen content." (PMID 34532344, 2021). "Osteogenesis imperfecta (OI) is a genetic disorder characterized by increased bone fragility, low bone mass, and growth deficiency mostly caused by mutations in collagen type I encoding genes (COL1A1 and COL1A2)." (PMID 33925433, 2021). "To date, the pathogenic genes of DGI type I, which is considered a clinical manifestation of syndrome osteogenesis imperfecta, include COL1A1 and COL1A2." (PMID 29575674, 2019). "Osteogenesis imperfecta (OI), also known as brittle bone disease, is a congenital bone disorder related to type 1 collagen alpha chains (COL1A1 and COL1A2) metabolism disorder that affects skeletal development." (PMID 29744175, 2017). "These disorders are categorized into major clinical groups, such as Skeletal Dysplasias (e.g., analysis of genes like ACAN, ACP5, and ACVR1), Osteogenesis Imperfecta (COL1A1, COL1A2, BMP1), Metabolic Disorders (ACE, AGT, BICC1), and Cardiomyopathies, among others." (PMID 40282387, 2025).